STAT3 (signal transducer and activator of transcription 3)
Diseases named in the same sentence as STAT3 in open-access papers (continued):
Sharing a sentence is not in itself a finding about the gene and the disease.
cancer (continued). "STAT3, a signal transducer and transcription activator, exhibits significant activation across a range of cancers and plays a pivotal role in promoting cell proliferation, inhibiting apoptosis, facilitating angiogenesis, and enabling immune evasion." (PMID 40772037, 2025). "The in vitro results showed the participation of redox APE1 and STAT3 in cellular processes essential to cancer, such as proliferation and aggressiveness." (PMID 41090323, 2025). "In this study, we addressed the possibility of blocking STAT3 signaling in neutrophils as a targeted therapeutic intervention in cancer." (PMID 40885734, 2025). "Research has demonstrated that STAT3 remains persistently activated in v‐Src‐transformed cells, suggesting its potential as a therapeutic target in cancer." (PMID 40166646, 2025). "Our findings reveal a novel regulatory axis in EBV-positive cancer cells involving STAT3, MYC, EBNA1, & ZC3H18, also linking ZC3H18 to the NF-κB pathway independently of LMP1." (PMID 40354417, 2025). "The JAK/STAT3 signaling pathway plays a pivotal role in cancer progression, frequently activated in HNSCC." (PMID 40231344, 2025). "While DDSs offer significant advantages for STAT3‐targeted cancer therapy, further research is necessary to address these limitations and ensure clinical feasibility." (PMID 40166646, 2025). "In lung cancer, STAT3 activation is associated with enhanced metastatic potential, aiding in epithelial-to-mesenchymal transition (EMT), which allows cancer cells to spread to distant organs." (PMID 40075607, 2025). "These M1-like TAMs secrete IL6, supporting EMT and cancer stem cells via the JAK/STAT3 pathway, thus creating a positive feedback loop." (PMID 39941858, 2025). "IL-6 activates STAT3 via the MAPK-STAT3 phosphorylation pathway, which supports cancer cell proliferation, survival, invasion, and metastasis." (PMID 40708946, 2025). "STAT3 signaling represents a key intrinsic pathway in cancer-related inflammation, as it is often activated in malignant cells and drives the expression of numerous genes essential for promoting inflammatory processes." (PMID 40149421, 2025). "In vivo studies further validated the role of TQ in stimulating apoptosis of A431 cancer cells by enhancing ROS production and disrupting the STAT3 signaling pathway." (PMID 40377005, 2025). "Mice deficient in both prostate-specific STAT3 and PTEN exhibit accelerated cancer progression and metastasis compared to mice deficient only in PTEN." (PMID 40430079, 2025). "Multiple signaling routes are linked to cancer advancement, notably the JAK/STAT3 pathway, which is crucial for inflammation and promotes tumor growth." (PMID 40867609, 2025). "JAK2/STAT3 is a classical inflammatory pathway that plays an important role in regulating the transition from inflammation to cancer." (PMID 41200213, 2025). "Inhibition of STAT3 in cancer not only decreases cell survival but can also reactivate the anticancer immune response, providing dual benefits." (PMID 40433378, 2025). "BBI608, a small molecule inhibitor of the STAT3 signaling pathway, has been shown to be effective in inhibiting stemness gene expression in LCSCs, inducing cancer cell death, and suppressing cancer recurrence and metastasis." (PMID 40135802, 2025). "This review explores cysteine alkylation as a cancer treatment strategy, focusing on Michael acceptors like curcumin and helenalin, which interact with transcription factors NF-κB, STAT3 and HIF-1α." (PMID 40507356, 2025). "The STAT3 transcription factor is often overactivated in cancers and plays an essential role in control of cell proliferation and cell death." (PMID 39985075, 2025). "Another possible way of addressing these toxicities is to improve the cancer cell-specific targeting of STAT3 inhibitors, such as through the use of antibody–drug conjugates." (PMID 40075607, 2025).
cancer (continued). "It has been shown to induce apoptosis and inhibit proliferation in various cancer cell types by targeting key signaling pathways, such as NF-κB, STAT3, and MAPKs." (PMID 40864795, 2025). "Many studies have shown that STAT3 induces the transcription of genes involved in cancer cell proliferation and survival, such as CCND1, BCL2, and MYC." (PMID 41104968, 2025). "MiR-384, a central player in cancer cell proliferation, metastasis, and progression, also regulates Th17 cell polarization, which requires STAT3 activation." (PMID 40660393, 2025). "In detail, STAT3 has been the subject of extensive research over the past decade to elucidate its significance and role in cancer." (PMID 39843641, 2025). "Natural compounds such as curcumin, resveratrol, and epigallocatechin gallate (EGCG) have been shown to downregulate STAT3 signaling in lung and other cancers." (PMID 40278288, 2025). "Increasing evidence indicates that redox-sensitive STAT3 signaling plays a crucial role in maintaining cancer stem cell (CSC) properties and promoting resistance to therapy." (PMID 40867898, 2025). "Cell cycle regulation is tightly linked to several key signaling pathways, including the JAK2/STAT3 pathway, which has been identified as a critical regulator of cell cycle progression and proliferation in many cancers." (PMID 40075566, 2025). "In summary, the data confirm that STAT1 and STAT3 have opposing roles in the cancer biology of NHLs." (PMID 40287766, 2025). "STAT3 is a family of transcription factors found to play a crucial role in maintaining cancer stem cells." (PMID 40696387, 2025). "The IL-6/JAK/STAT3 signaling pathway constitutes a self-sustaining regulatory circuit that plays a key role in both cancer development and progression." (PMID 40364836, 2025). "The reduced copper content not only inhibits tumor neovascularization, but also inhibits the phosphorylation of EGFR and STAT3, promotes ubiquitin-mediated degradation of PD-L1 and inhibits PD-L1 transcription, eventually blocks cancer immune escape." (PMID 39744687, 2025). "This review underscores the critical role of STAT3 in the pathophysiology of cancer cachexia, a debilitating syndrome characterized by progressive muscle wasting, systemic inflammation, and metabolic dysregulation." (PMID 40704145, 2025). "In OC, IL6 via STAT3 promotes the expression of CD44, a transmembrane glycoprotein associated with cancer cell stemness." (PMID 40427188, 2025). "Specifically, YTHDF3 was found to primarily target STAT3, a transcription factor that is frequently activated in human cancers and is involved in viral processes." (PMID 41453852, 2025). "Aberrant constant activation of STAT3 has been observed in several human cancers, including ovarian, head and neck, breast, or lung cancers, driving multiple oncogenic pathways." (PMID 41031165, 2025). "For example, studies show that CAFs secrete IL-6 and IL-11 to activate STAT3 signaling in cancer cells, enhancing survival and resistance to apoptosis." (PMID 40718440, 2025). "In cancer, STAT3 overexpression has been observed in many solid tumors, as well as in hematologic malignancies, correlating with unfavorable clinical stages, and the worst overall and disease-free survival." (PMID 40426911, 2025). "STAT3, a critical regulator of cell growth and metabolism, is known to influence the proliferation, migration, and apoptosis of cancer cells." (PMID 40530890, 2025). "In cancer, high IL-6 levels stimulate hyperactivation of JAK/STAT3, often linked to poor BC patient outcomes." (PMID 40868199, 2025). "The increase in p-STAT3 (Tyr705) in the nucleus subsequently initiates downstream signaling pathways, including the Hippo and Notch pathways in cancer cells, the VEGF pathway in endothelial cells and the PI3K-AKT pathway in T cells." (PMID 40430053, 2025).
cancer (continued). "Inflammatory mediators like Interleukin-6 (IL-6) and Tumor Necrosis Factor-alpha (TNF-alpha) activate STAT3 and NF-κB signaling pathways to promote cancer cell proliferation." (PMID 40475789, 2025). "The combination of immune checkpoint inhibitors, such as anti‐PD‐1 or anti‐PD‐L1 antibodies, with STAT3 inhibitors represents a promising strategy for cancer therapy." (PMID 40166646, 2025). "This interplay between chronic inflammation, metabolic dysfunction, and immune dysregulation underscores STAT3’s pivotal role in cancer cachexia pathogenesis." (PMID 40704145, 2025). "A-to-I recoding of BLCAP prevents its interaction to STAT3, leading to the activation of STAT3 signaling and cancer progression." (PMID 39126156, 2025). "STAT3 has been reported to play a critical role in the regulation of inflammation and the growth of cancer cells." (PMID 40444012, 2025). "This compound is designed to inhibit the phosphorylation of STAT3, a critical step in its activation and subsequent role in promoting cancer cell growth and survival." (PMID 40860906, 2025). "This study complemented these findings by demonstrating that in CRC, Prkci specifically activated the Jak2/Stat3 pathway, which was known for its involvement in cancer cell survival, proliferation, and angiogenesis." (PMID 40840329, 2025). "By disrupting STAT3 signaling, a pathway often activated in NSCLC and associated with drug resistance, W2014-S effectively inhibited cancer cell proliferation, survival, migration, and invasion in 3D cultures." (PMID 39790707, 2025). "Among them, STAT3 is often found hyperactivated in lung and other cancers, contributing to carcinogenesis and drug resistance." (PMID 39985075, 2025). "In another study, it was observed that EGCG can inhibit Stat3 and nuclear factor-kappa B (NF-kB) in cancer cells, resulting in the decreased expression of VEGF in breast cancer cells." (PMID 40563255, 2025). "A downstream transcription factor of the cytokine IL-6 is STAT3, which plays an indispensable role in the development of various cancers, including CRC." (PMID 40558596, 2025). "Based on our results, we can suggest that the depletion of NANOG or STAT3 through RNAi results in the sensitization of cancer cells to therapeutic agents." (PMID 40729003, 2025). "For example, cancer cell-intrinsic STAT3 activation fosters secretomes that recruit and polarize neutrophils, while silencing STAT3 in G-MDSCs restores T cell proliferation and cytokine secretion." (PMID 40358184, 2025). "Constitutive activation of STAT3 is relevant to cancer development and progression in many types of malignancies." (PMID 41104968, 2025). "Among the seven different STAT proteins identified in mammals, STAT1 and STAT3 are the most intensely studied family members given their prominent and partially antagonistic roles in immune reactions and cancer development." (PMID 40287766, 2025). "We found that ECGs were significantly enriched in the TNF‐α/NF‐κB, KRAS and IL‐6/JAK/STAT3 pathways across nearly all cancer types." (PMID 40576208, 2025). "Given the critical role of STAT3 in cancer pathogenesis, inhibiting its phosphorylation represents a promising therapeutic approach (Tošić and Frank 2021)." (PMID 40860906, 2025). "Another in vivo study in a mice model focused on targeting the signal transducer and activator of transcription 3 (STAT3) signaling, which plays a major role in cancer stem cells maintenance." (PMID 40284417, 2025). "We examined the expression levels of cyclin B, Cdk1, cyclin D1, PCNA, JAK1, STAT3, and other cancer pathway components." (PMID 40350446, 2025). "Specifically, constitutive phosphorylation of STAT3 at Tyr705 has been observed in a broad spectrum of cancers, including prostate, breast, gastric, bladder, lung, intestinal, and ovarian cancers, as well as in lymphoma and glioma." (PMID 40141386, 2025).
cancer (continued). "While STAT3 is well established as a promising therapeutic target across multiple cancer types, significant gaps in our understanding remain." (PMID 40075607, 2025). "M2 macrophages activate PI3K/AKT/mTOR and JAK1/STAT3 signaling cascades in cancer cells, and this leads to the progression of GC and the development of resistance to 5-fluorouracil." (PMID 39941714, 2025). "The blended H2.1MS1:MS2KN spheres were effectively loaded with oligonucleotides and delivered siSTAT3 to HER2+ cancer cells that successfully silenced STAT3 expression." (PMID 40584785, 2025). "Our study revealed that B7‐H3 directly interacts with c‐Met, triggering c‐Met/STAT3 phosphorylation and enhancing cancer cell stemness in vitro and in vivo." (PMID 40859957, 2025). "STAT3, frequently constitutively activated in cancer cells, promotes inflammation-driven tumorigenesis by regulating genes involved in cell survival, proliferation, and immune evasion." (PMID 41226270, 2025). "In cancer cells, the persistent activation of STAT3 contributes to uncontrolled cell proliferation, inhibition of apoptosis, promotion of angiogenesis, and metastasis (Valle‐Mendiola and Soto‐Cruz 2020)." (PMID 40860906, 2025). "In terms of adjuvant therapy, KLT increases cancer cell sensitivity to chemotherapeutics via JAK2/STAT3 and NF-κB pathway modulation, downregulating MDR1, MRP1, and PVT1, while mitigating chemotherapy-related adverse effects." (PMID 41164166, 2025). "Despite ongoing research, STAT3-targeting agents have yet to gain FDA approval for clinical use in cancer therapy." (PMID 40723906, 2025). "Phosphorylation of JAK and STAT3 is a critical step in the JAK/STAT signaling pathway, whose dysregulation has been implicated in various diseases, including cancer." (PMID 40321161, 2025). "In this review, we evaluate the current STAT3 inhibitors and discuss the implications of targeting Y705, S727, or both residues for safe and effective cancer treatment." (PMID 40075607, 2025). "Signal Transducer and Activator of Transcription 3 (STAT3) is an oncogenic transcription factor often overactivated in various cancers, making it an appealing drug target." (PMID 39997178, 2025). "As a downstream pathway of the IL–6/STAT–3 axis, STAT–3 is a hot topic in cancer and inflammation research." (PMID 40005889, 2025). "OC exerts its anti-cancer effects by inhibiting crucial oncogenic signaling pathways, including c-Met and STAT3, which play pivotal roles in cancer cell proliferation, survival, and metastasis." (PMID 40564985, 2025). "Napabucasin is a STAT3 inhibitor that mainly acts on cancer stem cells, but a quantitative proteomics analysis of the napabucasin-based PROTAC molecule XD2-149 revealed that XD2-149 significantly reduces the level of ZFP91." (PMID 40362266, 2025). "This leads to enhanced survival of cancer cells, especially under oxidative stress, through the activation of STAT3." (PMID 40558596, 2025). "In myotubes in vitro, the silencing of Hsp90 or STAT3 protects from the atrophy induced by C26 cancer cell conditional media (C26‐CM) and decreases the expression of Atrogin‐1, Myostatin and MuRF1." (PMID 39707668, 2025). "For instance, concanavalin A and silibinin are found to inhibit gatric cancer via attenuation of the JAK/STAT3 signaling pathway based on molecular docking analysis." (PMID 40708058, 2025). "Disruption of STAT3 signaling in neutrophils impairs cancer development; however, the mechanism involved in this phenomenon is not clear." (PMID 40885734, 2025). "The STAT3 signaling pathway has been well-characterized as a critical driver of cancer metastasis through its regulation of matrix metalloproteinases (MMPs)." (PMID 40564932, 2025).
cancer (continued). "JAK/STAT3 pathway dysregulation correlated with an increased proliferation and angiogenesis in cancer and with various immunodeficiency syndromes." (PMID 40698088, 2025). "At the same time, the inhibition of STAT3 has been shown to inhibit the development of cancer, invasion, and migration by inhibiting EMT processes." (PMID 40830747, 2025). "Together, these findings demonstrate that LIF produced by cancer cells acts directly on muscles to cause atrophy, primarily through JAK2/STAT3 signaling." (PMID 40869331, 2025). "Upon activation by upstream interleukins, IL-17RB facilitates downstream signal transduction, triggering pathways implicated in cancer progression, including NF-κB, MAPK, and STAT3." (PMID 40630198, 2025). "Various chemical agents, such as industrial waste and hydrocarbon compounds, can alter the expression or signaling activity of AhR and STAT3 pathways, leading to different types of cancers." (PMID 40141386, 2025). "STAT3 was suggested to be a mediator connecting inflammation and cancer progression, in which silencing of the STAT3 was found to limit CRC cell growth and induce cell death at the G2/M stage." (PMID 39641861, 2025). "This aligns with CuB’s known mechanism of action in other cancers where it directly binds and inhibits STAT3 phosphorylation, triggering downstream effects like ROS elevation and ferroptosis." (PMID 41145734, 2025). "Inhibition of cell cycle progression, colony formation, proliferation, migration, invasion, and selective killing of STAT3-overactivated GC cells have been observed in various cancer cells treated with Lut25,36." (PMID 40520011, 2025). "Within the nucleus, PKM2 is a transcriptional coactivator that confers malignant potential to cancer cells through its association with various transcription factors including Oct-4, HIF-1α, β-catenin, and STAT3." (PMID 40059196, 2025). "JIB-04, a histone demethylase inhibitor, targets epigenetic regulators involved in stemness pathways, while napabucasin, a STAT3 inhibitor, blocks key transcriptional pathways that promote cancer stem cell survival." (PMID 40160820, 2025). "It promotes cancer growth through activation of the STAT3 pathway, enhancing cell proliferation, survival, angiogenesis and metastasis." (PMID 41376630, 2025). "Our study identified core genes (ALB, BCL2, EGFR, IL-6, and STAT3) enriched in cancer pathways, suggesting a potential link between cancer-related metabolic dysregulation and fatigue." (PMID 40435272, 2025). "IL-6, a pivotal regulator of inflammation, autoimmunity and cancer, predominantly exerts its function via the IL-6/STAT3 pathway." (PMID 41291543, 2025). "Specifically, sensitivity to cisplatin has been reported to increase when STAT3 is inhibited in various cancers 81, which is consistent with our findings." (PMID 40860181, 2025). "The current findings build upon this by revealing the interplay between ZFAS1, IGF2BP2, and STAT3, which appears to be an important mechanism driving cancer progression." (PMID 40697388, 2025). "This review provides a comprehensive overview of the molecular mechanisms by which STAT3 contributes to cancer cachexia and discusses emerging therapeutic strategies aimed at modulating STAT3 activity to mitigate the progression of this debilitating syndrome." (PMID 40704145, 2025). "The downregulation of PTEN activates the PI3K/Akt and STAT3 signaling, resulting in increased accumulation of cancer-promoting molecules like IL-10, CCL2, and VEGF-A, while simultaneously reducing the antitumor immune response." (PMID 40443670, 2025). "Key factors involved in DC activation in various carcinomas include STAT3 and NF-κB, which also regulate antigen presentation to T and B cells, highlighting the dual role of DCs in cancer progression and immune defense." (PMID 40136652, 2025). "Both IL-24 and WP1066, a specific STAT3 inhibitor, have been investigated as cancer therapies in clinical trials." (PMID 40175348, 2025).